ACTG1 (actin gamma 1)
Description:
Actins are highly conserved proteins that are involved in various types of cell motility and are ubiquitously expressed in all eukaryotic cells. May play a role in the repair of noise-induced stereocilia gaps thereby maintains hearing sensitivity following loud noise damage (By similarity).
Synonyms: ACTG; ACT; DFNA20; DFNA26; HEL-176
Tractability: Small molecule: a structure with a bound ligand is known. Antibody: its Gene Ontology location is reachable by antibodies, with high confidence. PROTAC: ubiquitination databases record sites on it; its protein half-life has been measured.
Safety:
Unwanted effects reported when the protein is acted on. In parentheses: how it was acted on, where the effect was seen, and who reports it.
grade 3-4 neurotoxicity (source: ClinPGx)
Gene: Protein-coding gene on chromosome 17 (81,509,413 to 81,523,847, reverse strand). Ensembl gene ENSG00000184009.
Subcellular location: Cytoplasm, cytoskeleton
Pathways (Reactome):
Disease: FCGR3A-mediated phagocytosis; Paradoxical activation of RAF signaling by kinase inactive BRAF; Signaling by BRAF and RAF1 fusions; Signaling by RAF1 mutants; Signaling by high-kinase activity BRAF mutants; Signaling by moderate kinase activity BRAF mutants; Signaling downstream of RAS mutants
Signal Transduction: MAP2K and MAPK activation; RHO GTPases Activate Formins; RHO GTPases Activate WASPs and WAVEs; RHO GTPases activate IQGAPs; RHOBTB2 GTPase cycle; VEGFA-VEGFR2 Pathway
Cell-Cell communication: Activation of STAT3 by cadherin engagement; Adherens junctions interactions; Cell-extracellular matrix interactions; Regulation of CDH1 Function
Developmental Biology: EPH-ephrin mediated repulsion of cells; EPHB-mediated forward signaling; Interaction between L1 and Ankyrins; Recycling pathway of L1
Vesicle-mediated transport: Clathrin-mediated endocytosis; Formation of annular gap junctions; Gap junction degradation; Translocation of SLC2A4 (GLUT4) to the plasma membrane
Immune System: GBP-mediated host defense; Regulation of actin dynamics for phagocytic cup formation
Sensory Perception: Sensory processing of sound by inner hair cells of the cochlea; Sensory processing of sound by outer hair cells of the cochlea
Extracellular matrix organization: Formation of the dystrophin-glycoprotein complex (DGC)
Gene Ontology:
Molecular function: identical protein binding; profilin binding; protein binding; ubiquitin protein ligase binding; ATP hydrolysis activity; protein kinase binding; structural constituent of cytoskeleton; structural constituent of postsynaptic actin cytoskeleton
Biological process: angiogenesis; morphogenesis of a polarized epithelium; platelet aggregation; positive regulation of cell migration; positive regulation of gene expression; positive regulation of wound healing; protein localization to bicellular tight junction; regulation of focal adhesion assembly; regulation of stress fiber assembly; regulation of transepithelial transport; tight junction assembly; axonogenesis; cell motility; maintenance of blood-brain barrier; cytoskeleton organization; postsynaptic actin cytoskeleton organization; regulation of synaptic vesicle endocytosis
Cellular component: actin filament; apical junction complex; blood microparticle; cell-cell junction; extracellular exosome; extracellular region; membrane; nucleus; actin cytoskeleton; axon; cytoplasm; cytoskeleton; cytosol; dense body; focal adhesion; NuA4 histone acetyltransferase complex; plasma membrane; synapse; apical part of cell; basal body patch; calyx of Held; filamentous actin; myofibril; phagocytic vesicle; Schaffer collateral - CA1 synapse
Genetic constraint (gnomAD): Loss-of-function variants: 14 observed, 35.47 expected, observed/expected ratio (o/e) 0.39, 90% interval 0.26 to 0.62. The synonymous counts are far from expectation, so gnomAD's model fits this gene poorly and the ratio says little. Missense variants: 233 observed, 545.79 expected, observed/expected ratio (o/e) 0.43, 90% interval 0.38 to 0.48. Synonymous variants: 421 observed, 223.37 expected, observed/expected ratio (o/e) 1.88, 90% interval 1.73 to 1.98.
Gene-disease validity (ClinGen):
ClinGen rates the evidence that ACTG1 causes each of these diseases.
Baraitser-winter syndrome 2 (autosomal dominant): Definitive.
nonsyndromic genetic hearing loss (autosomal dominant): Definitive.
Homologues: Orthologues: chimpanzee ACTG1 (100% identical), guinea pig ACTG1 (100% identical), macaque ACTG1 (100% identical), mouse Actg1 (100% identical), pig ACTG1 (100% identical), rat Actg1l1 (100% identical), tropical clawed frog actg1 (99% identical), zebrafish actb1 (99% identical), zebrafish actb2 (99% identical), dog ACTG1 (67% identical). Paralogues in human: ACTB (99% identical), ACTA2 (94% identical), ACTC1 (94% identical), ACTG2 (94% identical), ACTA1 (93% identical), ACTBL2 (91% identical), ACTR1B (56% identical), ACTR1A (55% identical), ACTRT3 (50% identical), ACTR2 (49% identical), ACTRT2 (49% identical), ACTRT1 (48% identical), and 14 more.
Diseases named in the same sentence as ACTG1 in open-access papers:
ACTG1 is named in the same sentence as 126 diseases in open-access papers, as found by Europe PMC text mining. Sharing a sentence is not in itself a finding about the gene and the disease. The quoted sentences say what the papers report.
hearing loss (19 papers, 2012 to 2024). "This deficit is thought to be related to the presence of the ACTG1 gene variant, as several papers report an initial hearing impairment in the early years of life, limited to high frequencies." (PMID 38592426, 2024). "The review of the literature on the clinical features of the pathogenic variants of the ACTB and ACTG1 genes shows a significantly higher incidence of hearing impairment in ACTG1 gene variants than in those of the ACTB gene." (PMID 38592426, 2024). "Since the early 2000s, an ever-increasing subset of missense pathogenic variants in the ACTG1 gene has been associated with an autosomal-dominant, progressive, typically post-lingual non-syndromic hearing loss (NSHL) condition designed as DFNA20/26." (PMID 34698053, 2021). "The shared clinical features of NAA80 individuals and ACTB/ACTG1 individuals, for example hearing loss, suggest a similar underlying pathophysiological mechanism." (PMID 34805998, 2021). "The estimated onset age for ACTG1-associated hearing loss is, therefore, considered to be about 14 years old." (PMID 32341388, 2020). "DE3395 is a late-onset hearing loss patient who was found to have p.(Thr277Ile) (c.830C>T) in ACTG1." (PMID 30682115, 2019). "The novel mutation p.K213R in ACTG1 was found to be co-segregated with hearing loss and the genetic cause of ADNSHI in this family." (PMID 26832775, 2016). "In family 1, subjects III:3 and IV:2 with hearing loss had a unique heterozygous missense mutation of ACTG1 (c.802G >A; p.G268S), whereas subject III:4 with normal hearing did not." (PMID 24164807, 2013). "It is important to note that ACTG1 c.773C>T (p.Pro258Leu) was previously reported in a patient with a similar clinical presentation to Patient 2: progressive sensorineural hearing loss, intellectual disability, and interestingly enough, visual impairments, an uncommon feature in BWS2." (PMID 39734360, 2024). "Another actin-coding gene, ACTG1, is associated with brain development and hearing loss." (PMID 30967896, 2019). "Also the eight ACTG1 mutations (T89I, K118N, K118M, E241K, P264L, T278I, P332A, V370A) involved in progressive hearing loss in autosomal dominant isolated neurosensory deafness type DFNA lead to specific changes in polymerization and F-actin severing by the actin-binding protein cofilin." (PMID 32349449, 2020). "Analysis of the ACTB gene found fewer papers reporting hearing impairment than analysis of the ACTG1 gene." (PMID 38592426, 2024). "This is the first report of mutations in ACTG1, POU4F3, and SLC26A5 in Japanese families with hearing loss." (PMID 24164807, 2013). "Most individuals with ACTB/ACTG1 variants that exhibit hearing loss have normal actin abundancy, but show altered actin dynamics in vitro, suggesting that altered actin dynamics rather than absolute actin concentrations contribute to hearing loss." (PMID 34805998, 2021). "Moreover, no pathogenic mutation was found in the ACTG1, KCNQ4, GJB3, or COCH genes in patients with late onset hearing loss and autosomal dominant pedigrees or in patients with sporadic hearing loss." (PMID 30344259, 2018).
deafness (17 papers, 2014 to 2025). An inherited or acquired condition characterized by the complete loss of the ability to hear from one or both ears. "ACTG1 (Actin Gamma 1) is associated with deafness, autosomal dominant inheritance, and Baraitser-Winter syndrome." (PMID 34955843, 2021). "Recently, several exome sequencing studies were carried out and ACTG1 mutations were identified as causes for either deafness or Baraitser-Winter syndrome." (PMID 26832775, 2016). "In this study, by using targeted sequencing of known deafness genes, we identified a novel mutation, c.638A > G (p.K213R), in ACTG1 in a Chinese autosomal dominant deafness family." (PMID 26832775, 2016). "In auditory cells, dominant progressive deafness is associated with multiple mutations in ACTG1." (PMID 40166371, 2025). "Both ACTG1-related non-syndromic A20/A26 deafness and B-WS diagnoses are characterized by hypervariable penetrance in phenotype." (PMID 35054877, 2022). "We further posit and present argument and evidence suggesting ACTG1-related non-syndromic DFNA20/A26 deafness is a manifestation of undiagnosed ACTG1-related B-WS." (PMID 35054877, 2022). "The del(GJB6-D13S1830), SERPINB6, TMIE, COCH, ESPN, ACTG1, GJB3, and KCNQ4 mutations were infrequently associated with deafness in the Moravian-Silesian population." (PMID 30344259, 2018). "Of them, three were novel missense mutations (p.G38D in COCH, p.E316K in ACTG1, and p.P164R in POU4F3), one was a novel in-frame indel mutation (c.2036-2038delAGG in WFS1), and two were known deafness-causing mutations that have been previously reported (p.R653C in WFS1 and p.D572N in TMC1)." (PMID 25388789, 2014). "One example is monoallelic variants in the ACTG1, coding for gamma (γ)‐actin, which is associated with classical Baraitser‐Winter Syndrome type 2 (BRWS2) and a variety of clinical presentations not fitting the original BRWS2 description including non‐syndromic deafness." (PMID 39734360, 2024). "The most frequent causative deafness gene was TMC1 (DFNA36) (3 cases), followed by the next tier of genes (2 cases each) (CDH23, COCH, SLC26A4, TMPRSS3, ATP1A3), and the genes that were detected only once (ACTG1, GJB2, ILDR1, MYO7A, MYO15A, NF2, NLRP3 and SERPNB6)." (PMID 32238869, 2020). "The most frequent causative gene revealed by this technology was CDH23 (n = 3), followed by MYO15A (n = 2), MYO7A (n = 2) and other four deafness genes (PCDH15 (n = 1), USH2A (n = 1), MYO3A (n = 1) and ACTG1 (n = 1))." (PMID 25373420, 2014). "This patient also displays brachycephaly and a complete absence of speech faculty, previously unreported for ACTG1-related B-WS or DFNA20/26 deafness, representing phenotypic expansion." (PMID 35054877, 2022). "Hotspot mutations in the deafness-associated genes are not uncommon, and have been reported for KCNQ4, ACTG1, WFS1, and TECTA." (PMID 32486382, 2020). "Interestingly, among others PSMC3 was shown to interact with CHMP4B (MIM 610897), ACTG1 (MIM 102560) and GJB6 (MIM 604418) involved in cataract and deafness." (PMID 32500975, 2020). "Monoallelic variants in ACTG1, coding for gamma (γ)‐actin, are associated with classical Baraitser‐Winter Syndrome type 2 (BRWS2, nonsyndromic deafness, and a variety of clinical presentations not fitting the original BRWS2 description or nonsyndromic deafness." (PMID 39734360, 2024). "Our finding adds evidence to the extreme variability and broad spectrum of ACTG1‐related disorders, ranging from classical BRWS2 to nonsyndromic deafness, and occasionally new observed clinical features." (PMID 39734360, 2024).
Baraitser-Winter syndrome (14 papers, 2013 to 2025). "A thoroughly phenotyped patient with OCS and ACTG1-associated Baraitser-Winter cerebrofrontofacial syndrome is presented." (PMID 36205783, 2022). "In summary, this case provides evidence of OCS in ACTG1-associated Baraitser-Winter cerebrofrontofacial syndrome." (PMID 36205783, 2022). "This paradigmatic case provides evidence of syndromic OCS in ACTG1-associated Baraitser-Winter cerebrofrontofacial syndrome." (PMID 36205783, 2022). "Some ACTG1 mutations are associated with Baraitser-Winter syndrome, which is characterized by developmental delay, facial dysmorphologies, brain malformations, colobomas, and variable hearing loss." (PMID 23506231, 2013). "Further, missense mutations in either ACTB or ACTG1 have recently been reported to cause Baraitser-Winter syndrome." (PMID 23506231, 2013). "ACTG1 mutations can also cause a brain malformation (Baraitser-Winter syndrome) in humans." (PMID 40166371, 2025). "Loss-of-function variants in NIPBL cause Cornelia de Lange syndrome; missense variants in ACTG1 lead to Baraitser-Winter syndrome; missense variants in ATP1A3 underlie Snijders Blok-Campeau syndrome; and loss-of-function variants in TCF4 result in Pitt-Hopkins syndrome." (PMID 41300846, 2025). "To investigate the pathogenesis underlying this cortical malformation, we studied patient-derived cerebral organoids from induced pluripotent stem cells of individuals with the Baraitser-Winter-CerebroFrontoFacial syndrome (BWCFF-S) carrying an ACTB/ACTG1 missense mutation." (PMID 41372632, 2025). "Likewise, individuals with ACTB and ACTG1 variants and Baraitser-Winter syndrome frequently present with neuronal migration disorders like lissencephaly and pachygyria resulting in mild intellectual disability and seizures." (PMID 34805998, 2021). "Baraitser-Winter syndrome (BRWS) is a rare genetic disorder caused by mutations in the ACTB and ACTG1 genes." (PMID 38361693, 2024). "Different gain-of-function pathogenic variants of ACTG1 have been associated with two major phenotypes: DFNA20/26 and Baraitser-Winter syndrome, a multiple congenital anomaly disorder." (PMID 34698053, 2021). "Baraitser-Winter Syndrome (B-WS, OMIM #243310, #614583) is a rare, multiple-anomaly genetic disorder caused by mutations in either cytoplasmically expressed actin gene, ACTB (β-actin) or ACTG1 (γ-actin)." (PMID 35054877, 2022). "So far, an association between obsessive–compulsive symptoms (OCS) and ACTG1-associated Baraitser-Winter cerebrofrontofacial syndrome has not been described as yet." (PMID 36205783, 2022). "It is notable that within this region, none of the deletions include ACTG1, which is implicated in Baraitser-Winter syndrome 2, an autosomal dominant disorder characterized by neuronal migration defect, distinctive face, and cardiac defects including bicuspid valve, VSD and PDA." (PMID 26070612, 2015).
breast carcinoma (9 papers, 2017 to 2024). "LongGF also detected more potential novel gene fusions (ACTB:H3F3B, SLC25A24:NBPF6, STMN1:ACTG1), and these genes were reported to be associated with breast cancer." (PMID 33372596, 2020). "For example, dysregulation of ACTG1 has been reported in lung cancer, colorectal cancer, prostate cancer, and breast cancer." (PMID 38339062, 2024). "We thus performed correlation analysis between the 6 actin genes (ACTA1, ACTA2, ACTB, ACTC1, ACTG1, and ACTG2) 18 and the ABPs involved in translocation/polymerization and transcriptional regulation of nuclear actin in breast cancer through the GEPIA2 web-based platform." (PMID 39308680, 2024). "A few of NETs-related genes are highly expressed in breast cancer, such as ACTB, ACTG1, KRT10." (PMID 37304069, 2023).
hepatocellular carcinoma (9 papers, 2019 to 2025). A malignant tumor that arises from hepatocytes. "For example, hepatocellular carcinoma induced by hepatitis B virus X-protein (HBx) was associated with systemic dysregulation of ACTG1." (PMID 40166371, 2025). "Actin gamma 1 (ACTG1) mRNA levels, recognized as a biomarker for alcohol-associated hepatocellular carcinoma, were considerably increased by long-term ethanol treatment with PDMS devices for 120 h." (PMID 38715085, 2024). "Former studies have assured that ACTG1 is an oncogene in hepatocellular carcinoma and colorectal adenocarcinoma." (PMID 35349390, 2022). "ACTG1 was shown to induce cancer cell migration in lung cancer cells and hepatocellular carcinoma cells." (PMID 31675377, 2019). "Furthermore, ACTG1 acts as a tumor promoter in different cancers, such as skin cancer, hepatocellular cancer, and lung cancer." (PMID 38806963, 2024). "A former study has reported that ACTG1 expedites glycolysis in hepatocellular carcinoma." (PMID 35349390, 2022).
colorectal cancer (6 papers, 2015 to 2025). A primary or metastatic malignant neoplasm that affects the colon or rectum. "Some data indicated a role of β- and γ-actins in carcinogenesis: components of the Arp2/3 complex were up-regulated in colorectal cancers, increased ACTG1 and reduced ACTB levels were identified in osteosarcoma analysis." (PMID 26008973, 2015). "Moreover, ACTG1, previously identified as a target of miR-10a in colorectal cancer, was also found to be strongly upregulated in human HCC cells." (PMID 41296454, 2025). "In colorectal cancer cells, ectopic expression of ACTG1 may delay cell adhesion." (PMID 40166371, 2025). "Further evidence revealed that miR-10a-5p targets matrix metallopeptidase 14 (MMP14) and actin gamma 1 (ACTG1), both of which positively regulate BCL-2 levels and render cancer cells resistant to anoikis in colorectal cancer cells." (PMID 33435156, 2021).
Intellectual disability (6 papers, 2015 to 2025). "That is the case of ACTG1 (MIM 102560) that causes BRWS2; (MIM 614583), a rare autosomal dominant (AD) condition with developmental delay/intellectual disability of variable degree and craniofacial dysmorphisms as the main clinical presentations." (PMID 39734360, 2024). "Dominantly inherited mutations in ACTG1 have been described in BRWS2, characterized by variable degrees of developmental delay/intellectual disability and distinct craniofacial findings as the main clinical presentations." (PMID 39734360, 2024). "After consolidating intellectual disability gene lists from two databases and one recent review article, we identified eight LRRK2 interacting proteins that have previously been linked to intellectual disability: ACTB, ACTG1, ATRX, DYNC1H1, HERC2, PPP2R1A, TUBA1A, and YWHAE." (PMID 31963867, 2020). "De novo mutations in the ACTB and ACTG1 genes, which encode β-actin and γ-actin respectively, have been identified in patients with BWCFF syndrome, which exhibit clinical similarities with DIAL syndrome e.g., microcephaly, growth retardation, immunodeficiency, intellectual disability and seizures." (PMID 40368919, 2025).
skin cancer (6 papers, 2020 to 2025). "Downregulation of ACTG1 resulted in the suppression of growth in A431 skin cancer cells, whereas its overexpression significantly promoted cell growth." (PMID 39000458, 2024). "ACTG1 was highly expressed in skin cancer tissues, and it may regulate the proliferation and migration of A431 cells through the ROCK signaling pathway." (PMID 40166371, 2025). "In particular, retinal density– and FD-lowering alleles at several PoPS-prioritized genes showed associations with higher risk of skin neoplasms, malignant melanoma, and eye cancer (IRF4/DUSP22, SLC45A2); a separate set of loci showed associations with lighter skin color (GNB2, ACTG1)." (PMID 34743558, 2022). "The extracted data underscore that the somatic mutations in ACTB and ACTG1 do not occur haphazardly across cancers and that the higher frequency observed in two skin cancer and two DLBCL studies merits further investigation." (PMID 32349449, 2020).